RAD52 (RAD52 DNA repair protein)
Diseases named in the same sentence as RAD52 in open-access papers (continued):
Sharing a sentence is not in itself a finding about the gene and the disease.
rectal cancer (4 papers, 2016 to 2023). A primary or metastatic malignant neoplasm that affects the rectum. "For instance, cervical and rectal cancer cells with low RAD52 expression were associated with poor response to platinum-based chemotherapies and increased resistance." (PMID 36980703, 2023). "As an attempt, we also investigated the possible association between RAD52 and survival in rectal cancer patients treated with chemo- and radiotherapy." (PMID 32143539, 2020). "Future studies should address the mechanisms underlying the prognostic implications of RAD52 in rectal cancer." (PMID 32143539, 2020). "Increased genomic instability as a result of SSA may promote cancer growth and spread, which could explain our observation that high levels of RAD52 are associated with poor survival outcomes in rectal cancer patients." (PMID 32143539, 2020). "Therefore, differences in oxidative and replicative stress conditions between the TC and TP may be one factor underlying the TC-specific correlation, with RAD52 expression and patient survival outcomes in rectal cancer." (PMID 32143539, 2020). "Considering these varied roles of RAD52, we aimed to explore its potential as a prognostic marker for rectal cancer and as a predictor of tumour response to neoadjuvant therapy in rectal cancer patients." (PMID 32143539, 2020). "We have analysed the impact of RAD52 expression on survival outcomes of patients with rectal cancer." (PMID 32143539, 2020). "This suggests that RAD52 expression has potential prognostic value in rectal cancer patients with LN-positive tumours." (PMID 32143539, 2020). "RAD52 expression was examined in tumour samples from 179 patients who underwent surgery for rectal cancer, including a sub-cohort of 40 patients who were treated with neoadjuvant therapy." (PMID 32143539, 2020). "Future work including sequencing studies should address the possibility that HDR is indeed dysregulated in rectal cancer tissues with low RAD52 expression." (PMID 32143539, 2020). "Our findings show that RAD52 expression is a potential prognostic factor for rectal cancer, with elevated levels of RAD52 predicting poor survival outcome." (PMID 32143539, 2020). "Due to the fact that RAD52 is known to promote SSA-mediated DNA repair in mammalian cells, it is possible that high levels of RAD52 result in increased levels of SSA repair in rectal cancer cells." (PMID 32143539, 2020). "After stratification for tumor site, two polymorphisms in RAD52 gene (rs1051669 and rs11571475) were associated with colon cancer risk while one SNP in NBN (rs14448) was associated with rectal cancer risk." (PMID 26735576, 2016). "Elevated RAD52 expression is related to worse DFS in patients with rectal cancer." (PMID 35210412, 2022). "In the preoperative rectal cancer tissues with lower levels of RAD52 seen in our study, it is possible that HDR was the primary mechanism of IR-induced DSB repair, and HDR may have compensated for the decreased SSA activity in these cells." (PMID 32143539, 2020). "Additionally, high expression of RAD52 correlates with a poor life span for rectal cancer patients." (PMID 36980703, 2023). "Our results suggested that RAD52 may have clinical value as a prognostic marker of tumour response to neoadjuvant radiation and both disease-free status and overall survival in patients with rectal cancer." (PMID 32143539, 2020).
cervical cancer (3 papers, 2012 to 2020). A primary or metastatic malignant neoplasm involving the cervix. "Another study has found that low RAD52 expression is associated with a poor response of cervical cancer cells to carboplatin." (PMID 32143539, 2020). "To evaluate the role of RAD52 variants in the response of tumor cells to platinum agents, we investigated their associations with platinum resistance and prognosis in cervical cancer patients." (PMID 23209746, 2012). "Therefore, both RAD52 variants and protein expression can predict platinum resistance, and RAD52 variants appeared to predict prognosis in cervical cancer patients." (PMID 23209746, 2012). "However, additional studies are needed to explore mechanisms underlying the observed low RAD52 expression levels that will be instrumental to cervical cancer chemotherapy." (PMID 23209746, 2012). "Thus, in correlating variants in DDR genes with protein expression and subsequent survival rates, variants in DDR genes such as RAD52 may be able to predict prognosis in cervical cancer patients." (PMID 28722656, 2017). "The positive expression rate (>2+) of RAD52 protein in cervical cancer tissues was 22% (30/139) compared to 88% in the normal tissues (15/17) (χ2-test, P<0.001)." (PMID 23209746, 2012). "The mean scores of RAD52 protein expression levels were 1.6±1.8 and 4.2±1.8 for cervical cancer and normal tissues, respectively." (PMID 23209746, 2012). "It was suggested that RAD52 SNPs, either individually or collectively, could modify gene function and alter RAD52 protein expression levels, making the cervical cancer cell resistant to platinum agents." (PMID 32143539, 2020). "Because these variant genotypes may predict the protein expression, we hypothesized that RAD52 protein expression levels may predict survival in cervical cancer." (PMID 23209746, 2012). "Consistently, in the present study, we found that the RAD52-negative protein expression status was associated with poor response of cervical cancer cells to carboplatin." (PMID 23209746, 2012). "Therefore, it seems biologically plausible that the RAD52-rs1051669 SNP may be functional by regulating RAD52 expression and thus contribute to platinum resistance in cervical cancer patients." (PMID 23209746, 2012). "In addition, the RAD52-negative rate was significantly associated with poor response of cervical cancer cells to carboplatin (Wilcoxon test, P = 0.028)." (PMID 23209746, 2012).
melanoma (3 papers, 2012 to 2019). A malignant, usually aggressive tumor composed of atypical, neoplastic melanocytes. "Although the overexpression of RAD52 was most predictive of poor RFS in melanoma, high RAD52 was not correlated with poor OS and short RFS in HCC." (PMID 31719794, 2019).
T-cell lymphoma (3 papers, 2017 to 2019). "Evidence that increased SSA is associated with cancer, come, e.g., from the examination of T-cell lymphoma in Ataxia Telangiectasia Mutated TM-deficient mice, which is suppressed following Rad52 deletion." (PMID 29335415, 2018). "Another study developed by this group, showed, using an in vivo ATM−/− mouse model, that RAD52 knockout seems to confer a longer latency period in T-cell lymphoma development, as well as an increase lifespan and decrease of tumor incidence when compared with the RAD52 wildtype model." (PMID 31652722, 2019). "This group found that knockout of the Rad52 gene in an in vivo ATM−/− mouse model led to not only an increased latency period to develop T-cell lymphoma, but also an increased lifespan and decreased overall tumor incidence in Rad52 knockout mice compared to Rad52 wildtype." (PMID 28722656, 2017).
triple-negative breast carcinoma (3 papers, 2017 to 2023). An invasive breast carcinoma which is negative for expression of estrogen receptor (ER), progesterone receptor (PR), and human epidermal growth factor receptor 2 (HER2). "As the first preclinical data for the prevention of brain metastasis of triple-negative breast cancer, these observations suggested that induction of DNA double-strand breaks by Vorinostat was associated with the downregulation of the DNA repair gene Rad52." (PMID 28722656, 2017). "Her6, compound heterozygote for RAD52 p.Tyr415Ter/delins, was diagnosed with ductal, triple-negative breast cancer at the age of 28 years." (PMID 37578974, 2023).
ataxia telangiectasia (2 papers, 2017 to 2018). Ataxia-telangiectasia is the association of severe combined immunodeficiency (affecting mainly the humoral immune response) with progressive cerebellar ataxia. "Shortly after RAD52 was found to be upregulated in liver cancer, a study by the Barlow group connected expression of the murine Rad52 gene with the disease Ataxia Telangiectasia (A-T)." (PMID 28722656, 2017).
candidiasis (2 papers, 2015 to 2018). Infection with the organism Candida. "Deletion of RAD52 or RTT109 also causes pseudohyphal cell morphology and strong virulence defects in mouse models of systemic candidiasis." (PMID 26473952, 2015).
cervical squamous cell carcinoma (2 papers, 2012 to 2019). A squamous cell carcinoma arising from the cervical epithelium. "We enrolled 154 patients with cervical squamous cell carcinoma, who had radical surgery between 2008 and 2009, and genotyped three potentially functional RAD52 variants by the SNaPshot assay." (PMID 23209746, 2012).
colon cancer (2 papers, 2016 to 2022). "In the present study, among CRC patients, and specifically those with colon cancer, carriers of the TT genotype of RAD52 rs11226 displayed a better survival while carriers of the MRE11A rs2155209 variant CC genotype showed a shorter survival." (PMID 26735576, 2016). "After adjusting for above significant covariates, CRC patients, particularly those with colon cancer carrying the TT genotype of RAD52 rs11226, displayed a longer survival in a recessive model (HR 0.70; 95% CI 0.52–0.93; p = 0.02 and HR 0.60; 95% CI 0.41–0.89; p = 0.01, respectively)." (PMID 26735576, 2016). "In HCT116 colon cancer cells we had previously found within 1h of GZ17-6.02 exposure that the expression of XPA and XPD had declined and the levels of RAD51 and RAD52 were enhanced." (PMID 36408163, 2022).
glioblastoma (2 papers, 2024 to 2026). The most malignant astrocytic tumor (WHO grade IV). "Summarizing, the synthetic lethality achieved by simultaneous inhibition of Polθ and PARP or Polθ and RAD52 is a promising approach to eliminate glioblastoma cells." (PMID 39273083, 2024). "Inhibition of Polθ or PARP1 or RAD52 produces a significant reduction in glioblastoma cell viability in comparison to the untreated control." (PMID 39273083, 2024). "The synthetic lethality achieved by combined inhibition of Polθ with other DNA repair proteins, such as PARP1 or RAD52, have an even greater effect on defeating glioblastoma; however, it needs to be studied in the broader context of its toxicity." (PMID 39273083, 2024). "In conclusion, we would like to highlight that Polθ inhibition used in combination with PARP1 or RAD52 inhibition has great potential to kill glioblastoma cells, and shows a synthetic lethal effect, while sparing normal astrocytes." (PMID 39273083, 2024).
lymphoma (2 papers, 2023 to 2025). A malignant (clonal) proliferation of B- lymphocytes or T- lymphocytes which involves the lymph nodes, bone marrow and/or extranodal sites. "Of these, one case with both lymphoma and salivary gland tumor was available for testing and was identified as RAD52 delins carrier." (PMID 37578974, 2023).
myelodysplastic syndrome (2 papers, 2013 to 2022). A clonal hematopoietic disorder characterized by dysplasia and ineffective hematopoiesis in one or more of the hematopoietic cell lines. "Four of these polymorphisms were located in oxidative damage/DNA repair genes (LIG1, RAD52, MSH3 and GPX3), which may play important roles in the pathobiology of myelodysplastic syndromes." (PMID 23339595, 2013).
Obesity (2 papers, 2021 to 2024). Accumulation of substantial excess body fat. "However, not all repair mechanisms may be equally affected as RAD52, a key protein for HR, is upregulated in FT placentas in obesity." (PMID 39092995, 2024).
serous ovarian cancer (2 papers, 2010 to 2025). "In analysis of The Cancer Genome Atlas datasets and immunohistochemistry of tissue microarrays, elevated RAD52 expression correlated with poor overall survival in patients with high-grade serous ovarian cancers." (PMID 41040355, 2025).
squamous cell carcinoma (2 papers, 2015 to 2020). A carcinoma arising from squamous epithelial cells. "This has been reported in RAD52-dependent progression of pre-malignancy to squamous cell carcinoma where RAD52 depletion appeared to increase genomic instability beyond a manageable threshold acceding the cells to death rather than tumorigenesis." (PMID 31799622, 2020). "Here, within 5,947 UADT cancers and 7,789 controls from 9 different studies, we found rs10849605, a common intronic variant in RAD52, to be also associated with upper aerodigestive tract (UADT) squamous cell carcinoma cases (OR = 1.09, 95% CI: 1.04–1.15, p = 6x10−4)." (PMID 25793373, 2015).
thyroid cancer (2 papers, 2014 to 2024). "Until now, few studies have been conducted to analyze the relationship between RAD52 polymorphisms and the risk of thyroid cancer." (PMID 38892180, 2024). "In the Saudi Arabian population, the RAD52 Gln221Glu polymorphic genotype and RAD52 2259C > T genotype, and variants thereof carrying a T allele, were reported to have a significantly higher risk of developing thyroid cancer." (PMID 24723911, 2014). "Only the combined variants of the RAD52, XRCC2, and XRCC3 genes showed an increased risk of thyroid cancer, as we wrote about in Section 3.2." (PMID 38892180, 2024). "Two other studies identified the combinations of RAD52 2259C > T, XRCC2 R188H and XRCC3 T241M polymorphisms and RAD51 Exon1/59G > T, XRCC3 Thr241Met variant alleles to have predictive value for the polygenic risk of thyroid cancer." (PMID 24723911, 2014).
Alzheimer disease (1 paper, 2025). A progressive, neurodegenerative disease characterized by loss of function and death of nerve cells in several areas of the brain leading to loss of cognitive function such as memory and language. "According to the results of GSE122063, GSE15222 and GSE48350 analysis, RAD52 mRNA was overexpressed in the Alzheimer’s disease group compared to Control group sampled from people without Alzheimer’s disease." (PMID 39796194, 2025).
bladder cancer (1 paper, 2023). "The four-locus models (APE1, RAD52, COMT, and MTHFR) for bladder cancer provided a prediction error of 0.78 and a CVC of 6.60 and 0.78 with a CVC of 7.40." (PMID 38137497, 2023).
bladder urothelial cancer (1 paper, 2020). "In the case of bladder urothelial cancer, low mRNA levels of RAD52 correlated significantly with a poor overall survival." (PMID 32143539, 2020).
breast tumor (1 paper, 2021). "Here, we first analyzed whether curcumin inhibited RAD52 in the breast tumor cell line MCF7 following DNA-damaging agent treatment." (PMID 33922657, 2021).
chronic myelogenous leukemia (1 paper, 2012). "If RAD52 is performing these functions in human cells, it may be a viable target for drugs to attenuate SSA events that contribute to therapy-related drug resistance and disease progression in patients with chronic myelogenous leukemia and other myeloproliferative disorders." (PMID 23170228, 2012).
gallbladder carcinoma (1 paper, 2021). "We identified a novel heterozygous germline RAD52 missense mutation in a patient with gallbladder carcinoma." (PMID 34106670, 2021).
germ cell tumor (1 paper, 2023). A benign or malignant, gonadal or extragonadal neoplasm that originates from germ cells. "KRAS, CDKN1B, CCND2, ETV6, and RAD52 mutations are the most common in germ cell tumors." (PMID 37958970, 2023). "The most prevalent changes in germ cell tumors are CDKN1B Amplification, KRAS Amplification, CCND2 Amplification, ETV6 Amplification, and RAD52 Amplification." (PMID 37958970, 2023).
Immunodeficiency (1 paper, 2023). Failure of the immune system to protect the body adequately from infection, due to the absence or insufficiency of some component process or substance. "RAD52 is functionally important in DNA repair, cancer susceptibility, and immunodeficiency." (PMID 37445737, 2023).
invasive breast carcinoma (1 paper, 2023). A carcinoma that infiltrates the breast parenchyma. "PBX2 and RAD52 protein expression levels in IHC are prognostic in invasive breast cancer patients." (PMID 37445737, 2023).
liver fibrosis (1 paper, 2020). "Additionally, both alleles together with RAD52 rs7963551 TT were more common in patients with lower liver fibrosis stage, confirming their role against liver damage progression." (PMID 33171788, 2020).
lung adenocarcinoma (1 paper, 2018). A carcinoma that arises from the lung and is characterized by the presence of malignant glandular epithelial cells.
lupus (1 paper, 2022). "Finally, Rad52 phosphorylation is associated with high levels of IgD CSR and anti-nuclear IgD autoantibodies in patients with systemic lupus erythematosus and in lupus-prone mice." (PMID 35190531, 2022). "Rad52-mediated Sμ–σδ CSR is required to mount an IgD-specific antibody response and is upregulated in systemic lupus erythematosus (SLE) patients and lupus mice, leading to high levels of total IgD and antinuclear antigen IgD autoantibodies." (PMID 35190531, 2022). "Further, consistent with the high levels of Rad52 and/or p-Rad52 expression and CSR to IgD, expression of ZFP318/Zfp318 was decreased in B cells of such SLE patients and lupus MRL/Faslpr/lpr mice." (PMID 35190531, 2022). "Thus, B cells expressing high levels of phosphorylated Rad52 would underpin the high levels of IgD and IgD autoantibodies to nuclear antigens in SLE patients and in lupus MRL/Faslpr/lpr mice." (PMID 35190531, 2022). "In both SLE patients and lupus MRL/Faslpr/lpr mice, the high level of CSR to IgD, total IgD and IgD nuclear autoantibodies likely stemmed from the higher level of B cell Rad52 and/or p-Rad52." (PMID 35190531, 2022).
myotonic dystrophy type 1 (1 paper, 2025). Steinert disease, also known as myotonic dystrophy type 1, is a muscle disease characterized by myotonia and by multiorgan damage that combines various degrees of muscle weakness, arrhythmia and/or cardiac conduction disorders, cataract, endocrine damage, sleep disorders and baldness. "Indeed, CGG repeat expansion in a fragile X model is independent of DSBR-mediated by Pol θ, RAD52, RAD54 or RAD54B100, and loss of Rad 52 or Rad54 has little effect on somatic CTG expansion in the brains of myotonic dystrophy type 1 (DM1) mice." (PMID 40501854, 2025).
rectal tumour (1 paper, 2020). "RAD52 may also hold potential as a predictive factor for rectal tumour response to preoperative radiotherapy, including response of LN-positive tumours, with low levels of RAD52 correlating with poor survival outcome." (PMID 32143539, 2020).
viral infection (1 paper, 2025). "RAD52 plays crucial roles in several aspects of mammalian cells, including DNA double-strand breaks repair, viral infection, cancer development, and antibody class switching." (PMID 39796194, 2025). "However, recent findings indicate that RAD52 participates in HRR, single-strand annealing, break-induced replication, the occurrence and development of cancer, viral infection, and antibody class switching, suggesting diverse and significant roles for RAD52 in mammalian cells." (PMID 39796194, 2025).
Werner syndrome (1 paper, 2021). "Other noteworthy findings of our study include a possible interaction between a newly identified locus, RAD52 and WRN, the Werner syndrome ATP‐dependent helicase." (PMID 34704651, 2021).